DLX1 (distal-less homeobox 1)
Description:
Plays a role as a transcriptional activator or repressor. Inhibits several cytokine signaling pathways, such as TGFB1, activin-A/INHBA and BMP4 by interfering with the transcriptional stimulatory activity of transcription factors, such as MSX2, FAST2, SMAD2 and SMAD3 during hematopoietic cell differentiation. Plays a role in terminal differentiation of interneurons, such as amacrine and bipolar cells in the developing retina (By similarity). Likely to play a regulatory role in the development of the ventral forebrain (By similarity). May play a role in craniofacial patterning and morphogenesis and may be involved in the early development of diencephalic subdivisions (By similarity).
Tractability: PROTAC: its protein half-life has been measured.
Gene: Protein-coding gene on chromosome 2 (172,084,740 to 172,089,677, forward strand). Ensembl gene ENSG00000144355.
Subcellular location: Nucleus
Subcellular location (Human Protein Atlas): Nucleoplasm; Cytosol; Vesicles
Gene Ontology:
Molecular function: protein binding; sequence-specific double-stranded DNA binding; DNA-binding transcription factor activity, RNA polymerase II-specific; RNA polymerase II cis-regulatory region sequence-specific DNA binding; chromatin binding; DNA binding; RNA polymerase II transcription regulatory region sequence-specific DNA binding
Biological process: cellular response to BMP stimulus; cellular response to transforming growth factor beta stimulus; negative regulation of BMP signaling pathway; negative regulation of cellular response to transforming growth factor beta stimulus; negative regulation of transcription by RNA polymerase II; positive regulation of transcription by RNA polymerase II; cell differentiation; embryonic skeletal system development; negative regulation of photoreceptor cell differentiation; positive regulation of amacrine cell differentiation; positive regulation of cell differentiation; regulation of transcription by RNA polymerase II; regulation of DNA-templated transcription
Cellular component: nucleoplasm; nucleus; chromatin
Genetic constraint (gnomAD): Loss-of-function variants: 7 observed, 24.07 expected, observed/expected ratio (o/e) 0.29, 90% interval 0.16 to 0.55. The upper end of that interval is the gene's LOEUF score, 0.55, which puts it in group 2 of 6, group 1 being the genes least tolerant of losing a copy. Missense variants: 233 observed, 343.34 expected, observed/expected ratio (o/e) 0.68, 90% interval 0.61 to 0.76. Synonymous variants: 155 observed, 146.36 expected, observed/expected ratio (o/e) 1.06, 90% interval 0.93 to 1.21.
Homologues: Orthologues: chimpanzee DLX1 (100% identical), macaque DLX1 (100% identical), dog DLX1 (99% identical), pig DLX1 (99% identical), rabbit DLX1 (99% identical), mouse Dlx1 (99% identical), rat Dlx1 (99% identical), guinea pig DLX1 (98% identical), tropical clawed frog dlx1 (80% identical), zebrafish dlx1a (78% identical), Drosophila melanogaster Dll (42% identical), Caenorhabditis elegans ceh-43 (33% identical). Paralogues in human: DLX6 (59% identical), DLX4 (42% identical), DLX5 (42% identical), DLX2 (37% identical), DLX3 (37% identical), NANOG (22% identical), NANOGP8 (22% identical), BSX (19% identical), VENTX (13% identical).
Diseases named in the same sentence as DLX1 in open-access papers:
DLX1 is named in the same sentence as 49 diseases in open-access papers, as found by Europe PMC text mining. Sharing a sentence is not in itself a finding about the gene and the disease. The quoted sentences say what the papers report.
prostate carcinoma (24 papers, 2009 to 2025). A carcinoma that arises from epithelial cells of the prostate gland. "Recently, a large multicenter trial including 1955 patients prior to initial prostate biopsy compared performance of urinary HOXC6 and DLX1 mRNA (combined with other risk factors) with Prostate Cancer Prevention Trial Risk Calculator (PCPTRC)." (PMID 33922626, 2021). "Distal-less homeobox 1 (DLX1) is reported as a prostate cancer (PCa) diagnostic biomarker, but the mechanism for its upregulation in PCa is unclear." (PMID 34493733, 2021). "We showed that HOXC6 and DLX1 are associated with different clusters of prostate tumor-specific enhancers and confer distinct transcriptomic changes upon knockdown in C42B prostate cancer cells." (PMID 27833659, 2016). "DLX1 encodes a distal-less homeobox 1 protein that is reported to drive prostate cancer metastasis." (PMID 27833659, 2016). "In prostate cancer, it reduces proliferation, invasion, and migration by targeting DLX1 and IGF-1R, while sponging by oncogenic lncRNAs such as SNHG11 and MYU relieves inhibition of c-MYC, highlighting its suppressive role." (PMID 41379397, 2025). "An increased expression of the DLX1 was seen in prostate cancer confirming the positive regulation of β-catenin signalling." (PMID 37876438, 2023). "For instance, DLX1 is a reliable biomarker for prostate cancer (PCa), and its elevated expression accompanies the development of aggressive phenotypes of the disease and poor patient survival." (PMID 37835497, 2023). "The SelectMDx (MDxHealth, Irvine, CA, USA) assay measures the mRNA levels of two genes, HOXC6 and DLX1, that are known to be overexpressed in aggressive prostate cancer." (PMID 36768533, 2023). "Distal-less homeobox-1 (DLX1) is a well-established non-invasive biomarker for prostate cancer (PCa) diagnosis, however, its mechanistic underpinnings in disease pathobiology are not known." (PMID 34493733, 2021). "SelectMDx is a test that combines clinical parameters (PSA, DRE, prostate volume, age and family history) with two urinary prostate cancer associated genes (HOXC6 and DLX1)." (PMID 32957584, 2020). "For example, HOXC6 and DLX1 genes, which are biomarkers and key players of prostate cancer development as well as genes involved cell cycle (CDK4, CDC23, MYC) and androgen signaling (AR, GRHL2) are found." (PMID 31515496, 2019). "HOXC6 is used in the SelectMDx prostate cancer urine test alongside DLX1." (PMID 36765747, 2023). "Overexpression of DLX1 in CD26+ prostate cancer cells compared to luminal cells has been shown." (PMID 27196083, 2016). "Interestingly, HOXC6 and DLX1 were recently identified as top markers for prostate cancer, but little is known about their target genes." (PMID 27833659, 2016). "However, different genes were identified upon knockdown of HOXC6 and DLX1, suggesting that each of these TFs has a distinct role in prostate cancer." (PMID 27833659, 2016). "By inspection, we also identified at least 10 additional transcription factors within 500 kb of 9 other GWAS loci, that are also reasonable candidates for contributing to prostate cancer risk: SOX13, ZFP36L2, ATOH8, DLX1 & DLX2 (same locus), GATA2, SKIL, SP8, ASCL2, and DPF1." (PMID 24497837, 2014). "This test measures the mRNA levels of three cancer-related genes: DLX1 (a prostate cancer cell proliferation gene), HOXC6 (a prostate cancer progression gene), and KLK3 (a prostate cancer reference gene)." (PMID 41374944, 2025). "Meanwhile, miR-129-5p binds downstream DLX1, ETV1 and CAMK2N1 targets to mediate the progression of prostate cancer and affect the biological functions of cancer cells." (PMID 39003446, 2024). "Re-introduction of miR-539 into prostate cancer cells inhibits expression of DLX1, leading to attenuation of TGF-β signaling, inhibition of proliferation, migration, and invasion, as well as growth of prostate cancer xenografts in mice." (PMID 31842336, 2019).
prostate carcinoma (continued). "Silencing of three genes (DLX1, PLA2G7 and RHOU) in the prostate cancer cell lines PC3 and VCaP by siRNA resulted in marked growth arrest and cytotoxicity, particularly in 3D organotypic cell culture conditions." (PMID 27196083, 2016). "This supports the recent finding that the combination of three genes (HOXC6, DLX1, and TDRD1) constitutes the top prognostic marker for prostate cancer." (PMID 27833659, 2016). "Interestingly, several well-known genes, despite being recommended for their utility in the identification of patients at risk of prostate cancer at RNA expression level, are by far not in the top of this list (e.g. in urine; PCA3, HOXC6, DLX1)." (PMID 31170942, 2019). "Some of these genes were already extensively studied in prostate cancer, mostly those upregulated in tumor tissue: SPINK1 (Top17, logFC 4.8), ETV4 (Top63, logFC 3.6), PCA3 (Top79, logFC 3.5), TDRD1 (Top86, logFC 3.4), AMACR (Top105, logFC 3.2), DLX1 (Top110, logFC 3.1), HOXC6 (Top268, logFC 2.3)." (PMID 31170942, 2019). "DLX1 may be involved in epithelial-neuronal cell conversion, as prostate cancer not infrequently displays neuroendocrine differentiation." (PMID 20021671, 2009).
autism (5 papers, 2005 to 2022). Persistent deficits in social interaction and communication and interaction as well as a markedly restricted repertoire of activity and interest as well as repetitive patterns of behavior. "Linkage studies in autism have identified susceptibility loci on chromosomes 2q and 7q, regions containing the DLX1/2 and DLX5/6 bigene clusters." (PMID 16266434, 2005). "Furthermore, polymorphisms in the Dlx1/2 genes have been associated with an increased susceptibility for autism supporting the link between GABAergic anomalies and autism." (PMID 21876820, 2011). "Given the location of DLX1/2 and Dlx5/6 in relation to autism linkage intervals, other groups have examined whether DNA variants in these genes are significantly associated with autism." (PMID 16266434, 2005). "By site-directed mutagenesis of the Dlx1/2 intergenic enhancer regions, transgenic mice with autism-like phenotypes were generated, showing the possible role of disrupted Dlx1/2 in autism development." (PMID 35546872, 2022). "Furthermore, DLX1/2 and DLX5/6 are found on chromosomes 2q and 7q, which are autism susceptibility loci." (PMID 35546872, 2022). "Thus it is interesting that both the DLX1/2 and DLX5/6 loci have been implicated in autism via independent studies, including a common polymorphism in the DLX5/6 enhancer itself." (PMID 21765815, 2011). "The human DLX genes are organized as bigene clusters on chromosomes 2q31.1 (DLX1/2) and 7q21.3 (DLX5/6) and their expression is controlled by intra- and extragenic enhancers These genes are close to loci that have been linked with autism (2q32, and 7q22-31)." (PMID 16266434, 2005).
ovarian carcinoma (5 papers, 2018 to 2024). A malignant neoplasm originating from the surface ovarian epithelium. "FOXM1 recognizes two conserved binding sites that flank the TSS of DLX1, thus upregulating its expression in high-grade ovarian cancer." (PMID 37835497, 2023). "It is likely that FOXM1b and FOXM1c have common transcriptional targets, given the similarities of the proteins as well as data showing that both isoforms can target oncogenic DLX1 in ovarian cancer cells." (PMID 34205406, 2021). "The homeobox protein DLX-1 is a mediator in TGF-β1/SMAD4 signaling in ovarian cancer, which promotes EMT and cell stemness phenotypes." (PMID 34205406, 2021). "DLX1 has also been found to promote ovarian cancer cell growth, cell migration, and invasion." (PMID 30097071, 2018). "Finally, in ovarian cancer, DLX1 is a direct target of Forkhead Box M1 (FOXM1) TF." (PMID 37835497, 2023). "As for DLX1, it has been suggested as an important target of FOXM1 to enhance the aggressiveness of ovarian cancer." (PMID 33740948, 2021). "DLX1 hosts enhanced MYCN binding, predominantly enriched across a DNA stretch of ~1 kb that flanks its TSS and encompasses the core promoter, as well as TFBSs for FOXM1 that were previously characterized in ovarian cancer." (PMID 37835497, 2023).
cervical cancer (4 papers, 2014 to 2024). A primary or metastatic malignant neoplasm involving the cervix. "DNA isolated from 49 tissue samples with no histological evidence for CIN (normal), from 43 samples diagnosed as CIN3 and from 54 cervical cancer tissues was bisulfite-treated and used in qMSP experiments for the five marker regions DLX1, ITGA4, RXFP3, SOX17, and ZNF671." (PMID 24647315, 2014). "The aim was to investigate the diagnostic value provided by methylation biomarkers of six tumor suppressor genes (ASTN1, DLX1, ITGA4, RXFP3, SOX17 and ZNF671) for cervical precancerous lesions and cervical cancer." (PMID 36803573, 2023). "In previous studies we have shown that hypermethylation of CpG islands in proximity to the genes DLX1, ITGA4, RXFP3, SOX17, and ZNF671 correlated with the presence of cervical precancerous lesions and cervical cancer." (PMID 30509219, 2018). "A methylation signature comprising the 5′ regions of the genes DLX1, ITGA4, RXFP3, SOX17 and ZNF671 specific for CIN3 and cervical cancer (termed CIN3+) was identified and validated." (PMID 24647315, 2014). "In cervical cancer a DNA hypermethylation marker panel consisting of the six marker regions ASTN1, DLX1, ITGA4, RXFP3, SOX17, and ZNF671 may be a useful tool for triaging HPV-positive women." (PMID 30509219, 2018).
epilepsy (3 papers, 2005 to 2021). A brain disorder characterized by episodes of abnormally increased neuronal discharge resulting in transient episodes of sensory or motor neurological dysfunction, or psychic dysfunction. "Mice null for Dlx1/2 fail to develop GABAergic cortical and OB interneurons and do not survive; Dlx1-null mice survive to adulthood but suffer from epilepsy." (PMID 24115953, 2013). "Finally, mice lacking Dlx1 have defects in subsets of cortical local circuit neurons that lead to their apoptosis and subsequent onset of epilepsy." (PMID 16266434, 2005). "Mice lacking DLX1 have epilepsy, a common feature in autistic patients." (PMID 16266434, 2005).
Anxiety (2 papers, 2014 to 2024). Intense feelings of nervousness, tension, or panic often arise in response to interpersonal stresses. "Next, we conducted an elevated plus maze test to assess anxiety-related behavior in Dlx1-mTOR Tg mice." (PMID 39280263, 2024). "The time spent in the outer zone was not changed, suggesting that Dlx1-mTOR Tg mice did not exhibit anxiety-like behavior." (PMID 39280263, 2024).
breast cancer (2 papers, 2010 to 2011). A primary or metastatic malignant neoplasm involving the breast. "Dlx-2 has been shown to be expressed at higher levels in human breast cancers compared to other Dlx genes, including Dlx-1, Dlx-3, Dlx-4, and Dlx-6, although its precise roles in tumor biology are not clear." (PMID 21917150, 2011). "In mammary tumors, the expression levels of DLX1, DLX3, DLX4 and DLX6 did not significantly differ from those observed in normal tissue (data not shown)." (PMID 21108812, 2010).
prostate tumor (2 papers, 2016 to 2022). "In a previous study, the investigators found that HOXC6 and DLX1 associate with different prostate tumor-specific enhancer clusters and confer distinct transcriptomic changes on C42B prostate cancer cells, which play a role in prostate tumor development." (PMID 36304471, 2022). "The top 2 TFs associated with the most tumor-specific enhancer probes in prostate tumors, HOXC6 and DLX1, are each associated with more than 100 tumor-specific enhancer probes." (PMID 27833659, 2016). "Interestingly, HOXC6 and DLX1, which we characterized above, were also found in these “common” links, suggesting that they may play a role in the development of the majority of prostate tumors." (PMID 27833659, 2016). "We further characterized several transcription factors linked to a large number of enhancers in each tumor type, including GATA3 in non-basal breast tumors, HOXC6 and DLX1 in prostate tumors, and ZNF395 in kidney tumors." (PMID 27833659, 2016).
schizophrenia (2 papers, 2020 to 2021). A major psychotic disorder characterized by abnormalities in the perception or expression of reality. "Other genes in this FOXP2 gene cluster include NRG3, ERBB4, DLX1, ROBO2, and ROBO2, all are susceptibility gene in schizophrenia and is related to development." (PMID 33658499, 2021). "Taken together, we posit that the decrease in Dlx1, Dlx5, and Lhx6 expression that we observed in our schizophrenia models may lead to the cell-specific deficits in interneuron development that are thought to play a key role in the pathophysiology of schizophrenia." (PMID 32497066, 2020). "In humans, reduced Dlx1 mRNA has been observed in the OFC and thalamus of schizophrenia patients." (PMID 32497066, 2020).
acute myeloid leukemia (1 paper, 2023). Acute myeloid leukemia (AML) is a group of neoplasms arising from precursor cells committed to the myeloid cell-line differentiation. "In aberrant hematopoiesis, such as in acute myeloid leukemia (AML), upregulated expression of DLX1 has been recorded as a downstream effect of activating mutations of fms-like tyrosine kinase 3 (FLT3), a frequent genomic alteration (~30%) that accompanies AML phenotypes." (PMID 37835497, 2023).
Anosmia (1 paper, 2022). An inability to perceive odors. "We have identified a gene regulatory network, Gsx1/2 – Dlx1/2/5/6 – GAD2/1/Sp8/Sp9 – Tshz1 – Prokr2, which governs OBiN development; mutations of some of these genes result in human Kallmann syndrome with abnormal olfactory function (anosmia or hyposmia)." (PMID 34374948, 2022).
astrocytomas (1 paper, 2014). "CpG islands located in the DLX1 gene region were shown to be hypermethylated in astrocytomas as well as in chronic lymphatic leukemia patients." (PMID 24647315, 2014).
bladder tumors (1 paper, 2023). "While DSC1 had a statistically significant difference in the bladder tumor to blood ratio, DLX1 had the opposite effect on the bladder tumor to blood ratio." (PMID 37876438, 2023). "From the identified signature gene set, MDGA2, GNLY, DLX1, and DSC1 were selected for expression analysis in bladder tumors and matching blood samples of 10 BLCA patients." (PMID 37876438, 2023).
cervical intraepithelial neoplasia (1 paper, 2025). "A panel of six methylation markers (ASTN1, DLX1, ITGA4, RXFP3, SOX17, ZNF671; GynTect® assay) has shown promise in diagnosing cervical intraepithelial neoplasia (CIN)." (PMID 40022051, 2025).
colon cancers (1 paper, 2022). "The second notable TF regulator, DLX1, is involved in cGMP-PKG signaling pathway, and this cyclic GMP (cGMP)/protein Kinase G (PKG) pathway has been identified as an endogenous apoptotic mechanism in a variety of cancers, notably breast and colon cancers." (PMID 34976314, 2022).
colorectal cancer (1 paper, 2021). A primary or metastatic malignant neoplasm that affects the colon or rectum. "To explore the DLX1 target genes which are involved in tumorigenesis, we analyzed publicly available chromatin immunoprecipitation sequencing (ChIP-Seq) data for DLX1 in colorectal cancer LoVo cells." (PMID 34493733, 2021).
dwarfism (1 paper, 2018). "Dlx1/2-deficient mice show a loss-of-GHRH-neurons and an increase of AgRP-neurons, and consistently develop dwarfism and consume less energy." (PMID 29795232, 2018). "Our finding that Dlx1/2cKO mice show dwarfism, an absence of GHRH-neurons, and dysregulated GH signaling establish Dlx1/2 as essential players in the gene network directing the development of GHRH-neurons." (PMID 29795232, 2018).
dysplasia (1 paper, 2025). A usually neoplastic transformation of the cell, associated with altered architectural tissue patterns. "DLX1 is by far the worst-performing marker in vulvar tissue showing a positivity of 80% in dysplasia-free controls." (PMID 40022051, 2025). "DLX1, by far the worst-performing marker in vulvar tissue, is positive in 80% of dysplasia-free controls." (PMID 40022051, 2025).
Huntington disease (1 paper, 2018). Huntington disease (HD) is a rare neurodegenerative disorder of the central nervous system characterized by unwanted choreatic movements, behavioral and psychiatric disturbances and dementia. "An enriched population of striatal MSN, the neuronal subtype primarily degenerated in Huntington’s disease (HD), can be derived using miR-9/9∗-124 in conjunction with CTIP2, DLX1/2, and MYT1L (CDM) factors." (PMID 30116172, 2018).